EZH2 (enhancer of zeste 2 polycomb repressive complex 2 subunit)
Diseases named in the same sentence as EZH2 in open-access papers (continued):
Sharing a sentence is not in itself a finding about the gene and the disease.
lymphoma (continued). "Mechanistically, EZH2 depletion/inhibition de-represses cell cycle inhibitor p21CIP1/WAF1 (p21 for short) encoding gene CDKN1A and induces apoptosis in lymphoma." (PMID 35169119, 2022). "In clinical experiments, EZH2 inhibitors were shown to impede the progression of many cancer types, including lymphoma and solid tumors." (PMID 35085106, 2022). "Among them are GSK126 and EPZ005687, inhibitors effective against EZH2 mutant lymphomas, and EI1, a low MW inhibitor that blocks diffuse large B-cell lymphoma proliferation." (PMID 35419278, 2022). "The GSK126 can affect both mutant and WT EZH2 with high selectivity and it prevents the growth of lymphoma in mice and currently, it has been introduced to clinic (phase I) for treatment of lymphoma." (PMID 35236381, 2022). "EPZ-6438 selectively inhibited intracellular H3K27 methylation in a concentration- and time-dependent manner in both EZH2 wild-type and mutant lymphoma cells." (PMID 34721544, 2021). "Activation of NF-κB in response to cytokines and chemokines in tumor microenvironments promotes upregulation of EZH2 in leukemia and lymphoma cell lines." (PMID 34200679, 2021). "Optimized from EPZ-6438, EPZ011989 has a lower amine pKa, while the selectivity for EZH2 and potency against EZH2-mutant lymphoma are maintained (Ki < 3 nM)." (PMID 34617019, 2021). "One of the most frequent genetic alterations observed in germinal center B-cell (GCB) lymphomas such as Follicular lymphoma (FL) and DLBCL is mutations of EZH2 that affect the SET domain." (PMID 34200679, 2021). "Currently, EZH2 is reported to be highly expressed in lymphomas, glioblastoma multiforme, ovarian, breast, and metastatic prostate cancers and is related to tumor progression, invasive growth, and poor prognosis in these tumors." (PMID 35059393, 2021). "EZH2 expression is reportedly increased in murine prostate cancer (PCa) and lymphoma cell lines as well as in human primary tumor cells, such as breast cancer, melanoma, and pancreatic cancer." (PMID 33761979, 2021). "The EZH2 and HDAC epigenetic modifiers upregulated SLFN11 expression in GCB-derived lymphoma cells and made them more susceptible to cytosine arabinoside." (PMID 33513156, 2021). "Despite the opposing activities of EZH2 and the KDM6B demethylase in affecting H3K27me3 levels, both these enzymes have been implicated in both lymphoma development and drug resistance." (PMID 34200679, 2021). "The EZH2 inhibitor EZH2i blocks proliferation in EZH2 mutant DLBCL cell lines, and even in EZH2 wild-type lymphoma cells." (PMID 34207773, 2021). "Treatment with DzNep (EZH2 methyltransferase inhibitor) or ibrutinib increased FAS ligand-mediated apoptosis in lymphoma cell lines by abolishing the EZH2-mediated repression of FAS-AS1 expression, resulting in decreased expression of sFAS." (PMID 34502399, 2021). "It selectively inhibits H3K27 trimethylation of PRC2 in vitro and selectively suppresses the growth of leukemia and lymphoma cells by disrupting the EZH2-EED interaction." (PMID 34617019, 2021). "Some clinical trials are exploring the feasibility of EZH2 inhibitors in combination with immunotherapy for lymphoma and some solid tumors (NCT02220842, NCT03854474, NCT04407741, NCT03525795)." (PMID 34737746, 2021). "This suggests that GOF mutations in the SET domain of EZH2 can augment the sensitivity of lymphoma cells to the inhibition of either EZH2, SUZ12, or EED." (PMID 34202528, 2021). "Consistent with this, oncogenic mutations in Ezh2, combined with Bcl2 overexpression, also gave rise to early onset DLBCL lymphomas in Cγ1Cre;VavP:Bcl2;Ezh2Y641F/N and in irradiated wild-type mice transplanted with Ezh2Y641F-transduced VavP:Bcl2-derived HPCs." (PMID 34207773, 2021). "EZH2 inhibitors specifically target EZH2MUT lymphoma cells, restoring physiological H3K27me3 levels." (PMID 35008680, 2021). "Clarifying the relative contribution of inhibiting EZH1 together with EZH2 in lymphoma remains an important aspect to determine." (PMID 35071240, 2021).
lymphoma (continued). "There is growing interest in clinical development of EZH2 inhibitors in lymphoma, and selective EZH2 inhibitor have shown promising activity in EZH2 mutant cells." (PMID 32850364, 2020). "Suppression of HDAC3 and EZH2 cooperatively inhibited the MYC-EZH2-miR-29 axis, leading to reexpression of miR-29, therefore downregulating miR-29-targeted genes and inhibiting lymphoma progression." (PMID 32411322, 2020). "In several lymphomas, gain-of-function (GOF) EZH2 mutations targetingthe catalytic SET domain (Y641H, Y641S, Y641N, Y641F, A687V, or A677V) have beenidentified." (PMID 32453339, 2020). "Of note, MYC recruited EZH2 to miR-26a promoter repressing miR-26a expression in aggressive lymphoma cell lines as well as primary lymphoma cells." (PMID 32549409, 2020). "Considering the deregulation of PRC2 is associated with growth potential of lymphoma cells, targeting PRC2 with EZH2 inhibitors is a reasonable therapeutic approach to aggressive lymphomas." (PMID 32850364, 2020). "The second-generation compound CPI-1205 that has improved potency for inhibition of EZH2 is currently investigated in phase 1–2 clinical trials in lymphoma and solid cancers." (PMID 33371192, 2020). "GSK126 has been used in the study of lymphoma and other solid tumors to achieve the purpose of treating tumors by inhibiting EZH2." (PMID 33011750, 2020). "These analyses indicate that EZH2 (PRC2) can promote growth of lymphoma cells via suppression of cdkn2b and/or cdkn2a." (PMID 32850364, 2020). "GSK2816126, another EZH2-inhibitor, was recently investigated in a phase 1 clinical trial in lymphoma and solid cancers." (PMID 33371192, 2020). "EZH2 is an enhancer of H3K27me3, alteration of which are considered to be carcinogenic drivers of lymphoma and other malignancies." (PMID 33292221, 2020). "An EZH2 inhibitor, tazemetostat, is currently in multiple early phase clinical trials for both solid tumors and lymphomas, in combination with other agents including immunotherapy and chemotherapy (clinicaltrials.gov)." (PMID 33003334, 2020). "Astemizole, an FDA-approved H1 histamine receptor antagonist, was reported to arrest the proliferation of PRC2-driven lymphoma cells by disrupting the EZH2-EED complex." (PMID 32723346, 2020). "Mutations of the EZH2 gene increase repression via enhanced H3K27 trimethylation, and this transcriptional profile favors proliferation of lymphoma cells and results in the repression of plasma cell differentiation signatures." (PMID 33233721, 2020). "Given the importance of EZH2 dysregulation in cancers including lymphoma, there is growing interest in EZH2 inhibitors and a number of EZH2 inhibitors are under various stages of clinical development." (PMID 32850364, 2020). "Zhang and colleagues observed the epigenetic regulation of miR-29 by targeting HDAC3, MYC, and EZH2 in lymphomas." (PMID 32411322, 2020). "This leads to aberrantly high global levels of H3K27me3, with concomitant reductions of H3K27me2 levels in EZH2 mutant lymphoma cells." (PMID 31123059, 2019). "Despite first promising results, single-agent treatment with EZH2 inhibitors is in general slightly effective in aggressive lymphomas." (PMID 31681423, 2019). "EPZ-6438 selectively inhibits intracellular lysine 27 of histone H3 (H3K27) methylation in EZH2 wild-type and mutant lymphoma cells." (PMID 31704972, 2019). "In cutaneous anaplastic T cell lymphoma, EZH2 not only boosts lymphoma cell survival but also represses CXCL10 to hinder the recruitment of effector CD4+ and CD8+ T cells into the microenvironment, suggesting EZH2 possesses dual roles here." (PMID 31752930, 2019). "DLBCL lymphoma subtypes, as well as germinal center B-cell (GCB), primary mediastinal B-cell and ABC lymphomas, showed different percentages of mutations in ezh2, kmt2d, ep300, mef2b, and crebbp genes." (PMID 31921674, 2019).
lymphoma (continued). "We aimed to address the impact of the lymphoma type, EZH2 mutation status, as well as MYC, BCL2 and BCL6 translocations on the sensitivity of the lymphoma cell lines to DZNep-mediated apoptosis." (PMID 31419226, 2019). "EZH2 inhibitor EPZ6438 is currently under several clinical trials for multiple types of lymphoma, solid tumors and synovial sarcoma, such as clinical trials NCT03010982 and NCT01897571." (PMID 30287808, 2018). "Consistent with this, endogenous EZH2(Y641) mutants exhibit increased EZH2 stability and H3K27me3 hyperactivity in lymphoma cells." (PMID 30150556, 2018). "FBXW1ubiquitinatesEZH2, and Jak2-mediated phosphorylation on Y641 directsFBXW1-mediated EZH2 degradation, thereby controlling H3K27me3 activity and lymphoma pathogenesis." (PMID 29556394, 2018). "The reported EZH2-mediated epigenetic down-regulation of Sestrin1 increases the dependency of lymphomas on mTORC1 and induces sensitivity to mTORC1 inhibitors in EZH2 mutant lymphomas." (PMID 30110936, 2018). "Among these reports, altered EZH2 activity and levels have been most extensively documented in prostate, breast cancer, lymphoma, colon, myeloma, glioblastoma and medulloblastoma." (PMID 30761216, 2018). "For instance, EZH2 inhibitors have been applied to clinical trials in lymphoma and are suggested as promising therapeutic strategy in MM in combination with IMiDs and proteasome inhibitors." (PMID 28623912, 2017). "In EZH2-mutant lymphoma, selective EZH2 inhibitors have been shown to induce apoptosis, with minimal effects on EZH2 wild-type cells." (PMID 28685150, 2017). "Treatment of GC-derived lymphoma cell lines with EZH2 inhibitors was shown to induce CDKN1A mRNA expression." (PMID 29026085, 2017). "Preliminary data from the use of an EZH2 inhibitor, tazemetostat, in clinical trials of mutant and wild-type EZH2 lymphoma, demonstrated a favorable safety and efficacy profile to warrant a phase II trial stratified by mutation status." (PMID 28685150, 2017). "Using Basso’s Lymphoma dataset from Oncomine database, we previously showed that EZH2 mRNA is highly expressed in lymphomas compared to healthy donor’s B-lymphocytes." (PMID 27998273, 2016). "EZH2-specific inhibitors have been developed recently and their anti-cancer activity has been manifested in various cancer models including lymphomas." (PMID 26657505, 2016). "Several studies of hematopoietic system diseases have shown that EZH2 overexpression is involved in lymphoma and leukemia." (PMID 26812882, 2016). "CDKN1A/p21 and CDKN1B/p27 have also been reported to be EZH2 target genes in lymphoma cell line SUDHL4, and suppressed by H3K27-trimethylation." (PMID 27998273, 2016). "The milder apoptosis induction in wild type lymphoma cell lines compared with EZH2Y641 cells (where EZH2 catalytic activity is stronger) provided the proof of concept of the efficiency of these inhibitors." (PMID 26497210, 2016). "The anti-tumor effect of the EZH2 inhibitor GSK126 was detected in the lymphoma model at the concentrations of nanomoles." (PMID 26657505, 2016). "A number of EZH2 small molecule inhibitors have been developed and their antitumor efficacy has been tested in a number of tumor models such as lymphoma." (PMID 26657505, 2016). "A specific EZH2 inhibitor, GSK-126, has been shown to be active in EZH2-mutated lymphomas, and has yet to be tested in myeloid malignancies." (PMID 27023522, 2016). "Adult T-cell leukemia/lymphoma patient cells have increased expression of EZH2 that is inversely correlated with the expression of miR-101." (PMID 26882564, 2016).
lymphoma (continued). "High EZH2 expression in lymphomas is correlated with increased proliferation, tumor cell aggressiveness and poor prognosis." (PMID 26497210, 2016). "Other EZH2 mutations, including the EZH2 Y641 mutant, increase H3K27me3 catalytic activity in MDS and lymphoma." (PMID 26812882, 2016). "EZH2 activation and HOX inhibition predominate in lymphoma, while EZH2 inhibition and HOX gene activation are features of MDS." (PMID 26812882, 2016). "In cancer, EZH2 is over-expressed in multiple tumor types including lung, prostate, breast, colon, bladder, and pancreatic cancer, as well as sarcoma, lymphoma, and melanoma." (PMID 25671303, 2015). "Inhibition of EZH2 has been suggested to induce cell cycle arrest in G1 phase and antiproliferative response in the mutant-bearing lymphoma cell line WSU-DLCL2 (EZH2Y641F)." (PMID 26110843, 2015). "GSK343 was found to be less potent on all the other lymphoma lines, which express wild type EZH2, with anti-proliferative effects observed at micromolar concentrations of compound treatment." (PMID 26300989, 2015). "Proteomic analysis showed that EZH2 inhibition induced down-regulation of cell cycle regulators in lymphoma cells." (PMID 26110843, 2015). "These mutations occur in tyrosine 641 (Y641) residue within the catalytic SET domain of EZH2, and are found in two types of lymphomas: 21.7% of germinal center-type diffuse large B-cell lymphoma (GC-DLBCL) and 7.2% of follicular lymphoma (FL)." (PMID 25605023, 2015). "For example, a recent report proposes a regulatory loop linking overexpression of Myc, EZH2, and miR26a repression to lymphoma growth." (PMID 25987903, 2015). "Conversely, GRag/EPZ-6438 combination treatment also induced cell killing in those EZH2 mutant lymphoma cell lines that have been reported as refractory to EZH2 inhibitor treatment (RL, SUDHL4)." (PMID 25493630, 2014). "Given that only GRag+EPZ-6438 combinations induced dramatically enhanced anti-proliferative effects, compared to either single agent, in EZH2 mutant and three out of four EZH2 wild-type GCB lymphoma cell lines, we evaluated this combination in greater detail." (PMID 25493630, 2014). "This highlights the potential importance of overactive EZH2 in chemoresistance of EZH2 mutant lymphomas." (PMID 25493630, 2014). "Due to frequent activation of EZH2 in lymphoma, these new targeted therapies hold exciting promise in the clinic." (PMID 24622842, 2014). "The more recent EZH2 inhibitor GSK126 was also highly selective for mutant EZH2 lymphoma cells in vivo and led to increased activation of known EZH2 target genes, such as TXNIP and TNFRSF21." (PMID 24622842, 2014). "Potent EZH2 inhibitors that reduce levels of H3K27me3 kill mutant lymphoma cells and are efficacious in a mouse xenograft model of malignant rhabdoid tumors." (PMID 24367611, 2013). "For example, in lymphoma, a heterozygous missense mutation frequently occurs at amino acid Y641, within the SET domain of EZH2." (PMID 22187039, 2012). "EZH2 is highly expressed in a wide range of cancer types, including breast, prostate, bladder, colon, lung, pancreatic cancer, sarcoma and lymphomas Overexpression of EZH2 is often correlated with advanced stages of human cancer progression and poor prognosis." (PMID 22187039, 2012). "Abnormal overexpression of EZH2 has been reported in a wide variety of tumor types including carcinomas, lymphomas, cutaneous melanoma, and soft tissue sarcomas." (PMID 23110793, 2012). "Previous work in muscle, lymphoma and HeLa cells have shown that miR-26a and miR-26b can negatively regulate EZH2 expression, and that this occurs via binding to the highly conserved predicted miR-26a/b binding site within the 3′ UTR of EZH2." (PMID 21941025, 2011).
lymphoma (continued). "Our results suggest that this is the predominant long splice form of EZH2 in lymphoma and other tissues, and for this reason we prefer to designate the EZH2 codon affected by recurrent mutations in B cell lymphoma as Y641, rather than Y646." (PMID 22194861, 2011). "Since EZH2 plays a role in B-cell development in mice, it will be interesting to see, if human lymphomas show an increased methylation of lysine 27 (and possible lysine 9) in histone H3 at EZH2 target genes." (PMID 14970850, 2004). "Therefore, targeting EZH2 is considered a prominent approach to treating lymphoma, and tazemetostat, which specifically targets the EZH2 SET domain, has been approved for patients with follicular lymphoma and epithelioid sarcoma." (PMID 40562788, 2025). "Mutations in CREBBP (20%) and EZH2 (13%) were common in all progression cases of GCB COO, and lymphomas harboring alterations in these epigenetic modifiers may respond to histone deacetylase inhibitors and enhancer of EZH2 inhibitors, respectively." (PMID 39392347, 2024). "In addition, USP21 participates in the development of lymphoma through the stabilization of enhancer of zeste homolog 2 (EZH2), which is required for generating germinal centers and lymphoma tumors." (PMID 39664521, 2024). "Unlike lymphoma, EZH2 mutations in AML tend to be loss-of-function mutations, and studies indicate that loss-of-function EZH2 mutations in AML patients have poor prognoses and are associated with a reduced overall survival." (PMID 38339323, 2024). "The EZH2 inhibitor Valemetostat had an objective response rate (ORR) of 48% in a phase 2 clinical trial (NCT04102150) in the treatment of patients with relapsed or refractory (R/R) adult T-cell leukaemia/lymphoma (ALT)." (PMID 38644473, 2024). "Previous studies in lymphoma suggest that EZH2 inhibition can impact B cells regardless of the EZH2 mutational status." (PMID 38339323, 2024). "Together, the removal of H3K27me3 marks through PRC2 inhibition or depletion results in the upregulation of ACVR1 and the activation of BMP‐ACVR1 signaling, reflected by the phosphorylation of SMAD1/5 and the common upregulation of ID2 or ID3 in EZH2‐mutant lymphoma cells." (PMID 38229201, 2024). "In a clinical setting, EZH2 has emerged as a prominent factor in various lymphomas." (PMID 37760442, 2023). "Interestingly, cell proliferation was inhibited via apoptosis induction and cell cycle arrest in EZH2-mutant lymphoma cells if tazemetostat was applied." (PMID 36900361, 2023). "Older classes of epigenetic therapies, such as pan-HDAC inhibitors, are associated with high rates of toxicity and poor target selectivity, but newer classes, such as EZH2 inhibitors, have higher selectivity and better safety profiles and are being tested in a variety of lymphomas." (PMID 36871057, 2023). "In addition, a study of lymphoma pointed out that dysregulation of the GC, which result from constitutively active EZH2, activates lymphoma formation and identifies EZH2 as a possible therapeutic target for NHL and other GC-derived B-cell diseases." (PMID 37626362, 2023). "Furthermore, one patient with TP63 rearrangement in lymphoma showed a good response to valemetostat (EZH2 inhibitor), indicating that some fusions can increase therapeutic vulnerability to EZH2 inhibitors." (PMID 37998740, 2023). "Furthermore, we have evaluated EZH2 inhibition in a panel of leukemia and lymphoma cell lines with a focus on T-cell lymphomas characterized for canonical EZH2 signaling components." (PMID 37297005, 2023). "C-MYC is a well-known oncogene in lymphomas and is overexpressed in ENKTL, likely driven by LMP1 and EBV infection and causing upregulation of downstream targets EZH2 and RUNX3, the latter of which is a master transcriptional regulator and a putative oncogene in ENKTL." (PMID 36900160, 2023). "However, wild-type germinal center-derived lymphomas also retain dependency on EZH2 to proliferate and repress plasma cell differentiation." (PMID 36871057, 2023).